VDR (vitamin D receptor)
Diseases named in the same sentence as VDR in open-access papers (continued):
Sharing a sentence is not in itself a finding about the gene and the disease.
colitis (continued). "The important role of VDR as a nuclear receptor transcription factor in colitis and colorectal cancer has been confirmed by clinical and basic research." (PMID 40725244, 2025). "The potential interplay between probiotics and vitamin D arises from observations that probiotics have been shown to increase vitamin D absorption and increase vitamin D receptor (VDR) expression in the colon while reducing colitis severity in animal models." (PMID 40944110, 2025). "Vitamin D is integral in inhibiting this process, as it induces VDR signaling that prevents the activation of NF-κB through inhibition of IKK kinase, an enzyme implicated in colitis development and PUMA activity." (PMID 40243631, 2025). "In dextran sodium sulfate (DSS)-induced colitis in mice, selective deletion of the intestinal VD receptor (VDR) exacerbates colitis severity, leading to increased mucosal infiltration of Th1 and Th17 cells and a heightened inflammatory cytokine profile." (PMID 39685734, 2024). "Loss of the VDR and low circulating levels of 25(OH)D3 are observed in IBD, colitis and GvHD, highlighting the importance of VD3 in inflammatory conditions in the gut." (PMID 38495883, 2024). "Increased CYP27B1 expression and decreased VDR levels are observed in colitis, resulting in reduced inflammation and improved VDR signalling." (PMID 38279228, 2024). "For example, moderate hypoxia preserves the intestinal barrier in mouse dextran sulfate sodium (DSS)-induced colitis via HIF-1α modulation of Vitamin D Receptor (VDR) signaling." (PMID 38605960, 2024). "In the case of cancer associated with colitis, it has been shown to inhibit EMT via activation of the vitamin D receptor." (PMID 39519465, 2024). "Patrinia villosa improved TNBS-induced colitis by regulating BA metabolism, activating VDR, and inhibiting nuclear factor kappa B (NF-κB) signaling pathways." (PMID 39767816, 2024). "Epithelial VDR signaling plays an important role in the intestinal mucosal barrier and in protection against colitis." (PMID 36834927, 2023). "Further correlation analysis suggested the expressions of NHE8 and VDR proteins in colitis mice were positively related (n = 12, R = 0.653, p = 0.021)." (PMID 38004229, 2023). "In this study, we found that the oral administration of LCA attenuates DSS-induced colitis in a VDR-dependent manner." (PMID 36834927, 2023). "Because VDR is necessary for the effect of LCA on DAI scores and histological injury, VDR-mediated LCA signaling plays a main role in the protection against colitis." (PMID 36834927, 2023). "NF-κb p65 signaling activation has been suggested as a prominent mechanism involved in the development of colitis, and previous studies have demonstrated the regulatory role of VDR in NF-κb p65 signaling." (PMID 38004229, 2023). "Bile acids can act as signalling molecules, triggering both metabolic and immunoregulatory responses through binding to the nuclear receptors FXR, TGR5, and VDR, as shown in colitis and colon cancer models." (PMID 36768196, 2023). "Administration of butyrate also increases intestinal VDR expression and suppresses inflammation in a colitis model." (PMID 36672703, 2023). "Some reports have shown that patients with inflammatory bowel disease and colitis-related colon cancer have a significant decrease in VDR protein." (PMID 36830496, 2023). "In mouse model of colitis, VDR KO can exacerbate the symptoms in IL-10 KO mice, whereas vitamin D supplementation improves the symptoms." (PMID 37256134, 2023). "In the current study, we uncovered a novel mechanism by which VitD/VDR prevented intestinal barrier dysfunction by stimulating NHE8 expression in colitis, highlighting its promising role in repairing intestinal mucosal injury." (PMID 38004229, 2023). "It has been illustrated in some studies that intestinal epithelial VDR knockout mice have more severe colitis than wild‐type mice in TNBS‐induced colitis models." (PMID 36579449, 2023).
colitis (continued). "VDR deletion promotes colitis in mouse models, and VDR activation by vitamin D compounds suppresses inflammation." (PMID 36834927, 2023). "Vitamin D-treated IECs showed increased TEER, with upregulation of ZO-1, occludin, and several claudins, while VDR-deleted mice showed increased colonic permeability and susceptibility to DSS-induced colitis." (PMID 36678175, 2023). "The expression of tight junction proteins (occludin, ZO-1), HIF-1α as well as VDR was up-regulated in colitis mice with hypoxia stimulation." (PMID 35711312, 2022). "Our previous research on colitis mice suggested that the vitamin D–vitamin D receptor (VDR) pathway has a protective effect against colitis on the intestinal barrier." (PMID 35711312, 2022). "In experimental models, VDR knockout (KO) mice spontaneously developed colitis and VDR/IL-10 double KO mice developed severe IBD." (PMID 35406694, 2022). "All these data of experimental colitis in animal studies strongly support the pivotal role of vitamin D/VDR in maintaining an efficient mucosal barrier." (PMID 35057450, 2022). "It was demonstrated that claudin-2 is transcriptionally regulated by VDR in the healthy intestine; however, claudin-2 is hyper regulated through inflammatory signaling in colitis with reduced intestinal epithelial VDR." (PMID 35406694, 2022). "In this study, we found that hypoxia treatment had a protective effect on the intestinal barrier of mice with DSS-induced colitis and that VDR played a key role in it." (PMID 35711312, 2022). "The effect of histone H3 deacetylase was blocked in Vdr-/- mice, suggesting that histone deacetylation by MS-275 alleviated colitis by activating VDR." (PMID 36246903, 2022). "Our study revealed the beneficial effects of moderate hypoxia in mice with DSS-induced colitis and the key role of VDR in it." (PMID 35711312, 2022). "VDR favors FoxP3+ T reg cells, which prevent the development of experimental colitis through the production of inhibitory cytokines such as IL-10 and TGF-β and FoxP3+ T reg cells are induced by 1,25(OH)2D3 treatments in vitro and in vivo." (PMID 35057450, 2022). "The vitamin D-induced inhibition of T cells, reducing IFN-γ and IL-17 levels, and the induction of regulatory cells (T regs, CD8αα, and T) also supports the role of vitamin D/VDR in animal models of colitis." (PMID 35057450, 2022). "A previous study has shown that VDR-/- mice developed dramatic weight loss and a colitis phenotype in TNBS and DSS colitis models, while reconstitution of VDR-/- mice with the VDR transgene protected mice from developing colitis." (PMID 36142545, 2022). "has also shown that VDR signaling protected from DSS colitis, providing additional evidence for VDR in immune signaling by shifting macrophages towards the M2 phenotype." (PMID 36569849, 2022). "In various colitis models, VDR knockout mice displayed low levels of antimicrobial peptides, barrier dysregulation, and increased mortality." (PMID 35326394, 2022). "The intrinsic mechanism is that the VDR exerts an anti-apoptotic effect by inhibiting NF-κB activation in order to protect the intestinal barrier to relieve colitis." (PMID 36014889, 2022). "Data demonstrate that VDR plays a vital role in the epithelium, which in turn suggests that it either protects against the induction of colitis, or enables effective damage repair." (PMID 36233580, 2022). "Intestinal epithelial cells' (IEC) specific VDR knockout mice showed more severe colitis and higher expression of TNF-α, IL-1β, and MCP-1 than wild-type mice." (PMID 35600949, 2022). "Another mechanism study showed that VDR activates Claudin-15 (VDR’s target gene) to prevent colitis; this confirms the alleviating effect of vitamin D on IBD." (PMID 36014889, 2022). "LCA, DCA, and UDCA are suggested to interact with nuclear receptors including pregnane X receptor (PXR) and vitamin D receptor (VDR), both of which have been linked to protection from colitis (43, –, 46)." (PMID 35968955, 2022).
colitis (continued). "Restoring epithelial VDR expression with hVDR transgene alleviates severe colitis and reduces mortality." (PMID 36014889, 2022). "VDR was indispensable for mucosal barrier function under hypoxia in VDR-KO mice with DSS-induced colitis." (PMID 35711312, 2022). "Herein, we confirmed that 1) hypoxia exerts a barrier protective effect o in a DSS-induced mouse colitis model and VDR is instrumental in it and that 2) the regulatory role of HIF-1α on VDR in protecting the intestinal mucosal barrier." (PMID 35711312, 2022). "In fact, the deletion of intestinal epithelial VDR disrupts autophagy and its downstream cellular effects in colitis." (PMID 35008631, 2021). "The pathophysiological relevance of this bile acid-VDR signaling axis was demonstrated by showing that mice lacking VDR were more vulnerable to dextran sulfate sodium (DSS)–induced colitis." (PMID 34236487, 2021). "A study using an experimental colitis model with gut epithelial cell VDR knockout observed increased epithelial cell death, reduced intestinal barrier strength, and the consequent invasion of commensal gut microbes." (PMID 35008631, 2021). "In a report of VDR−/− colon inflammation mouse model, VDR knockout mice showed upregulation of IFN-γ+ and Interleukin 17+ (IL17+) T cells (Th1 and Th17) that results in the mucosa inflammation and the apoptosis of epithelium cells." (PMID 34740314, 2021). "On the other hand, administration of butyrate increased intestinal VDR expression and suppressed inflammation in a colitis model." (PMID 34680413, 2021). "Several of these common RNF20/RNF40/VDR targets were shown to be downregulated in experimental colitis, such as Muc2." (PMID 34088983, 2021). "More recently, its involvement in intestinal fibrosis has been reported and invalidation of VDR promotes intestinal fibrosis development in mice in response to DSS-induced colitis." (PMID 34579023, 2021). "Research showed that VDR−/− mice developed more severe colitis after TNBS treatment, along with increased intestinal epithelial cell apoptosis and mucosal barrier permeability." (PMID 34579027, 2021). "VDR inhibits necroptotic apoptosis, alleviates inflammation, and suppresses the induction of colitis by preventing receptor interacting serine/threonine kinase 3 (RIPK3) from binding to RIPK1." (PMID 34588980, 2021). "Jot and others showed that VDR also protects the intestines through the VDR-gut microbiota axis and reduces the susceptibility of DSS-induced colitis." (PMID 34588980, 2021). "Conversely, transgenic mice overexpressing VDR in the gut epithelium have resistance to colitis with decreased mucosal inflammation and apoptosis of epithelial cells." (PMID 33671090, 2021). "Intestinal VDR knockout mice had milder oxazolone-induced colitis than wildtype controls, as demonstrated by less body weight decrease and faster recovery, more intact local structure, reduced cell apoptosis, and better preserved barrier function." (PMID 32541827, 2020). "In conclusion, this study found that intestinal-specific VDR knockout protected against oxazolone-induced colitis in mice." (PMID 32541827, 2020). "In IL-10 knockout mice and DSS-induced colitis models, VDR exhibited protective effect on intestinal structure and barrier function." (PMID 32541827, 2020). "Probiotics have been shown to enhance VDR transcriptional activity, induce remission, reduce clinical activity scores, and prevent pouchitis, a complication in colitis following ileal pouch-anal anastomosis surgery." (PMID 32422882, 2020). "Knockout of the mouse genes for VDR (Vdr) or 1α-hydroxylase (Cyp27b1) shows increased severity of artificially induced colitis similar to IBD." (PMID 31286174, 2020).
colitis (continued). "In this study, we induced colitis in an intestinal-specific VDR knockout model in order to further clarify the role of intestinal vitamin D signaling pathway in oxazolone-induced colitis." (PMID 32541827, 2020). "Global VDR knockout mice had much more severe TNBS-induced colitis compared to their wild-type littermates." (PMID 32541827, 2020). "In an experimental colitis mouse model, VDR knockout mice developed more severe colitis with significant colonic epithelial cell apoptosis compared to control mice." (PMID 32422882, 2020). "This study investigated the influence of intestinal vitamin D receptor (VDR) knockout on oxazolone-induced colitis and explored the possible immunological mechanism." (PMID 32541827, 2020). "Intestinal VDR knockout protected against oxazolone-induced colitis in mice by blocking Th2 cell response and reducing the function of intestinal iNKT cells." (PMID 32541827, 2020). "In mice, deletion of the VDR increases mucosal injury that leads to high mortality in DSS-induced experimental colitis." (PMID 31139192, 2019). "In a cell transfer model of enteritis, CD4+ CD45RBhigh T cells from VDR KO mice induced more severe colitis in recombinase-activated gene (Rag) 2 KO recipient mice than CD4+ CD45RBhigh T cells from wild-type mice." (PMID 30804707, 2019). "We and others also documented that in mice models, 1,25(OH)2D3 deficiency or VDR knockout was correlated with an increased risk of colitis and 1,25(OH)2D3 supplement ameliorated DSS-induced colitis." (PMID 30828386, 2019). "IEC-specific VDR KO mice display worse colitis and higher expression of TNF-α, IL-1β, and MCP-1 than wild-type mice." (PMID 30804707, 2019). "Elegant studies in transgenic mice demonstrated that over-expression of VDR in the intestinal epithelium induces resistance to colitis and decreases mucosal inflammation suppressing epithelial cell apoptosis, boosting tight junction function." (PMID 30400332, 2018). "Lactobacilli are able to increase the expression of VDR target-gene encoding for cathelicidin, a cationic antimicrobial peptide, and to protect wild-type mice from Salmonella-induced colitis, while failing to inhibit Salmonella infective action in VDR−/− mice." (PMID 29562608, 2018). "On the other hand VDR selective deletion in bowel favors a more severe form of colitis characterized by greater Th1 and Th17 mucosal infiltration and inflammatory cytokines production." (PMID 30400332, 2018). "In a colitis model, administration of butyrate, a fermentation product of gut bacteria, increased intestinal VDR expression and suppressed inflammation." (PMID 29112157, 2017). "In support of this, IL-10−/− mice expressing the human VDR in intestinal epithelial cells resulted in a reduced development of spontaneous colitis." (PMID 28804483, 2017). "The anti-inflammatory role of 1,25(OH)2D3 is based on the suppressive effect of NFκB activity, as NFκB-induced pathways are enhanced in VDR−/− mice exposed to bacterial and chemically induced colitis." (PMID 28804483, 2017). "Interaction between the vitamin D axis and the gut microbiome was further demonstrated in a model of experimental colitis on CYP27b1 KO and VDR KO mice compared to littermates." (PMID 29112157, 2017). "Recently, it was suggested that VDR transgenic mice exhibit less colitis than wild-type mice, indicating the protective role of VDR in the development of intestinal inflammation." (PMID 25813397, 2015). "In the murine setting, IL-10−/− mice (an established mouse model for IBD) crossed with VDR−/− mice displayed exacerbation of colitis and fulminating inflammation when compared with VDR-sufficient control mice." (PMID 26347740, 2015). "DSS colitis in the VDR KO mice was accompanied by high colonic expression of TNF-α, IL-1 α, IL-1β, IL-12, IFN-γ, IL-10, MIP-1α and KC." (PMID 17397543, 2007).
colitis (continued). "In experimental colitis models using VDR knockout (VDR-/-) mice, animals exhibit increased vulnerability to epithelial damage, typically characterized by disruption of epithelial integrity and loss of tight junctions, which consequently increases susceptibility to bacterial translocation." (PMID 40534845, 2025). "Furthermore, butyrate supplementation has been found to increase VDR expression and suppress inflammation in colitis models." (PMID 40243631, 2025). "Furthermore, the protective effect of probiotics against Salmonella-induced colitis was completely abolished in VDR-knockout (KO) mice, suggesting a critical role for VDR activation in probiotic-mediated gut protection." (PMID 41304896, 2025). "Notably, a decrease in both the serum vitamin D levels and the expression of VDR in the colon has been observed in patients with colitis or colorectal cancer." (PMID 38318147, 2024). "LCA-dependent VDR activation suppressed the expression of proinflammatory cytokines in IECs during experimental colitis, and LCA had no anti-inflammatory effect in VDR-deficient mice." (PMID 38169949, 2023). "Moreover, we show for the first time that a novel microbiota-derived metabolite, 12-KLCA, exhibits a powerful anti-inflammatory effect in DSS-induced colitis by increasing the VDR expression and decreasing the IL-17A secretion in colonic ILC3s." (PMID 38062857, 2023). "We first investigated the protective effects of VitD/VDR in DSS-induced colitis mice." (PMID 38004229, 2023). "By using VitD-deficient mice, VDR−/−mice, NHE8−/− mice, Caco-2 cells and intestinal organoids, we perform a series of in vivo and in vitro experiments to elucidate the roles and mechanisms of VitD/VDR in the regulation of NHE8 in colitis." (PMID 38004229, 2023). "Experimental data from VDR−/− mice have revealed that VDR deletion could increase gut susceptibility and colitis deterioration responding to DSS insult." (PMID 38004229, 2023). "To address our speculations, we first estimated the effects of paricalcitol (vitamin D receptor activator) on NHE8 in colitis mice." (PMID 38004229, 2023). "In this study, we examined whether orally administered LCA exhibits a pharmacologic action on colitis in a mouse model and determined whether this effect is mediated by VDR." (PMID 36834927, 2023). "Additionally, VDR knockout mice experience more severe inflammation and higher death rates following experimentally induced colitis." (PMID 36816182, 2023). "Furthermore, the secondary bile acid LCA and its receptor VDR and VitD-regulated genes were elevated in mice with ameliorated colitis/CAC and treatment of LCA reduced lipid-induced proliferation and upregulated VitD genes in epithelial cells." (PMID 36768196, 2023). "Published evidence also supports that colonic VDR signaling upregulated by 1,25−dihydroxyvitamin D (1,25(OH)2D3) or microbial metabolites (bile acids, butyrate, etc.)contributed to the restoration of macrophage subtype balance, thus ameliorating colitis." (PMID 36992690, 2023). "Similarly, consistent changing trends of nuclear location and fluorescence intensity of pp65 were observed in VDR−/− colitis mice." (PMID 38004229, 2023). "Vitamin D signaling via VDR plays a protective role in experimental colitis." (PMID 36834927, 2023). "Intestinal epithelial cells-specific VDR KO mice showed a more severe colitis than WT mice." (PMID 37256134, 2023). "Maintaining the integrated functional mucosal barrier which inhibits colitis, VDR thus serves as the main defence mechanism against colitis, and in turn prevents the interaction between antigens and bacteria in intestinal lumen and immune components in the intestinal lamina propria." (PMID 36579449, 2023). "Interestingly, VDR/IL-10 double knockout (KO) mice develop colitis after 8 weeks as compared with single IL-10- or VDR-knockout animals that remain relatively healthy at that time." (PMID 35057450, 2022).